TNF (tumor necrosis factor)
Diseases named in the same sentence as TNF in open-access papers (continued):
Sharing a sentence is not in itself a finding about the gene and the disease.
psoriasis (continued). "Studies have revealed an association between psoriasis and polymorphisms in the TNFα promoter region, affecting its production and therefore suggesting a disturbance in the recognition of regulatory DNA target sites by transcription factors important for the expression of that gene." (PMID 33007857, 2020). "Therefore, TNF-α is probably one of the cytokines responsible for the increased risk of cardiovascular disease experienced by patients with psoriasis." (PMID 31275060, 2019). "However, overall psoriasis-associated genes and genes belonging to signaling pathways of IL-22, IFNγ, TNFα, IL-1, and IL-17 were more strongly suppressed by ustekinumab than by etanercept." (PMID 31673756, 2019). "The pathogenesis of psoriasis is mediated by a complex interplay between the immune system, inflammatory mediators of different pathways, e.g., TNF-alpha and the IL-23/IL-17 pathways, psoriasis-associated susceptibility loci, autoantigens, and multiple environmental factors." (PMID 31417571, 2019). "In addition to paradoxical psoriasis, TNF inhibition was reported to increase susceptibility to bacterial infections." (PMID 31295952, 2019). "In inflammatory state underlying psoriasis, resistin produced mainly by monocytes and macrophages in adipose tissue, could stimulate the secretion of pro-inflammatory cytokines, TNF-α and IL-12, by monocytes in NF-kB-dependent manner." (PMID 29416693, 2018). "Consequently, antibodies targeting the pathogenic TNF/IL-23/IL-17 pathway have revolutionised psoriasis treatment over the past 15 years and are widely used in the clinic today." (PMID 30555460, 2018). "Indeed, 6–7 days after tape stripping, the epidermis of anti-TNF treated mice showed typical hallmarks of psoriasis, including acanthosis, parakeratosis, and a focal loss of the granular layer." (PMID 29295985, 2018). "Furthermore, using the imiquimod-induced model of psoriasis, it was found that C3 deficient mice showed significantly reduced levels of IL-1β, TNF-α, IL-17a, and IL-23 in the skin and draining lymph nodes and decreased infiltration of neutrophils." (PMID 29713318, 2018). "But only 2–5% of anti-TNF treated patients develop paradoxical psoriasis indicating that there is another key determining factor such as genetic predisposition for paradoxical psoriasis." (PMID 30555460, 2018). "The singlenucleotide polymorphisms of TNF-α at loci + 489 GG and GA,−308 G/G, −238 and −857C/T and + 489 arestrongly associated with psoriasis and psoriasis arthropathica and may become avital pharmaceutical therapy target for these conditions." (PMID 29630472, 2018). "Various studies have also shown that systemic treatments for psoriasis, including methotrexate and tumor necrosis factor-α inhibitors, may significantly decrease cardiovascular risk." (PMID 29065479, 2017). "TNF inhibitors were associated with a significant lower risk of cardiovascular events compared with topical treatment/phototherapy (RR, 0.58; 95% CI, 0.43 to 0.77) and methotrexate treatment (RR, 0.67; 95% CI, 0.52 to 0.88) in patients with psoriasis." (PMID 29295598, 2017). "Various studies have shown that treatment of psoriasis patients with TNF-α inhibitors may lower the risk of cardiovascular comorbidities." (PMID 29065479, 2017). "Additionally, psoriasin is a chemotactic for CD4+ T cells and neutrophils, and is induced by psoriasis-associated inflammatory cytokines that include IL-1β, IL-17, IL-22, and TNF-α." (PMID 28360856, 2017). "Indeed, some studies demonstrated that the secondary psoriatic lesions developed during the course of anti-TNF treatment contain higher levels of IFN-alpha than those associated with idiopathic psoriasis." (PMID 28905102, 2017). "This supports earlier studies showing that TNF-α inhibition in psoriasis is associated with a substantial Th17 cell-count reduction in the patients’ peripheral blood and that this decrease is significantly associated with an adequate response to biologic therapy." (PMID 28005985, 2016).
psoriasis (continued). "Together with other cytokines, such as TNFα, IL-17, and IL-20, IL-22 therefore takes part in the formation of the cytokine network that orchestrates the progression of the different pathogenic features of psoriasis." (PMID 27595115, 2016). "It was demonstrated that skin treated with anti-TNF exhibits a downregulation of IL-24 expression in psoriasis patients, making the epidermal keratinocyte a direct target of pathogenic TNF signaling in psoriasis." (PMID 27271601, 2016). "Such pharmacological selectivity may be important to suppress inflammatory pathogenic circuits in psoriasis, while sparing the anti-infectious immune responses produced by TNF-α." (PMID 27184415, 2016). "The appearance of PLC has been described with the use of anti-TNF therapy, two cases in patients with Crohn's disease under treatment with adalimumab and two case reports with infliximab in a patient with psoriasis and another case with spondyloarthritis associated with ulcerative colitis." (PMID 25789178, 2015). "Moreover, psoriasis patients treated with TNF antagonists have a lower risk of new-onset diabetes than patients on non-biological disease-modifying antipsoriatic drugs." (PMID 26633680, 2015). "In addition, PSORS6 and TNFα have been described as more prevalent genes in type I psoriasis and we showed a significant association when we compared type I psoriasis and type II psoriasis." (PMID 26613086, 2015). "After treatment with the anti-TNFα drug Etanercept, the majority of psoriasis-associated alterations in circulating metabolites were reversed, shifting the metabolic phenotypes of severe psoriasis toward that of healthy controls." (PMID 26362816, 2015). "Additionally, HDBECs cultured with IL-17, TNFα, and IFNγ, three cytokines heavily implicated in psoriasis pathogenesis, resulted in upregulation of IL-8, CXCL1, CXCL10, and CCL5." (PMID 25369198, 2014). "Indeed, previous studies suggested that TNF-α production from dendritic cells (DCs) is essential for activation of the pathogenic IL-23/Th17 axis in psoriasis." (PMID 25384035, 2014). "Moreover, the authors found an association between the A allele in rs361525 in the TNFα gene and increased production of TNFα and early onset of psoriasis." (PMID 24069534, 2013). "Therefore, we conducted a systematic review and meta-analysis of previous published case-control studies to comprehensively evaluate the associations of TNF-α 308 G/A and 238 G/A polymorphisms with psoriasis risk." (PMID 24324571, 2013). "Therefore, the meta-analysis suggests that TNF-α 308 G/A polymorphism is associated with decreased risk of psoriasis, while TNF-α 238 G/A is associated with increased risk of psoriasis." (PMID 24324571, 2013). "Subgroup analysis by ethnicity identified a significant association between TNF-α 308 G/A polymorphism and decreased risk of psoriasis in both Caucasians and Asians and a significant association between TNF-α 238 G/A polymorphism and increased risk of psoriasis in Caucasians." (PMID 24324571, 2013). "Meta-analysis of the association between TNF-α 308 G/A polymorphism and psoriasis risk." (PMID 24324571, 2013). "Therefore, the genetic polymorphisms in TNF-α gene can have some effects on the hosts’ susceptibility to psoriasis by the changed TNF-α expression, and TNF-α 308 G/A and 238 G/A polymorphisms are the two most commonly studied." (PMID 24324571, 2013). "Besides, the associations of TNF-α 308 G/A and 238 G/A polymorphisms with psoriasis risk in other races also need further studies." (PMID 24324571, 2013). "Meta-analysis of the association between TNF-α 238 G/A polymorphism and psoriasis risk." (PMID 24324571, 2013). "Downregulation of CTGF by psoriasis-associated cytokines INFγ and TNFα is already published." (PMID 24303025, 2013).
psoriasis (continued). "Sixteen case-control studies with a total of 2,253 psoriasis cases and 1,947 controls on TNF-α 308 G/A polymorphism and fourteen studies on TNF-α 238 G/A polymorphism with 2,104 cases and 1,838 controls were finally identified from three main databases, including Pubmed, Embase, and Web of Science." (PMID 24324571, 2013). "It has been recently suggested that treatment with TNF-inhibitors or hydroxychloroquine may reduce the risk of diabetes in both psoriasis and PsA." (PMID 23843781, 2013). "In addition, IL-17A plays an important role in cutaneous defense by the cooperation with other psoriasis-associated cytokines such as IL-22, TNF-α and IL-1 which have been implicated in a synergistic induction of AMP in keratinocytes." (PMID 23555696, 2013). "A metaanalysis study suggested that TNF-α −238G/A and −308G/A polymorphisms might be used as biomarkers for psoriasis risk prediction." (PMID 23284977, 2012). "Since psoriasis is characterized by a systemic inflammation which involves numerous cytokines and inflammatory markers in particular TNF-α, it may predispose the patients to metabolic disorders." (PMID 22654590, 2012). "A causal link between psoriasis and cardiovascular disease is hypothesized also for the involvement of the same mediators and markers of inflammation, mainly TNF-α, IL-6, fibrinogen, and C-reactive protein." (PMID 22645622, 2012). "This has not been extensively studied but it is thought that the alteration in immunity caused by anti-TNF therapy may precipitate psoriasis in pre-disposed individuals." (PMID 20062693, 2009). "A TNF-α promoter polymorphism or a gene in linkage disequilibrium with TNF-α may predispose or increase susceptibility to psoriasis and PsA." (PMID 16138929, 2005). "Such reflections arise from the fact that patients with psoriasis are thought to be at increased risk of malignancies, and the biological agents may target some molecules that affect anti-cancer immune response (particularly TNFα)." (PMID 41481132, 2026). "Similarly, a large population-based analysis suggested that inflammatory disorders characterized by systemic TNF-α activity, including psoriasis, may elevate AD risk, whereas anti-TNF-α therapy appears to mitigate this effect." (PMID 41299626, 2025). "Similarly, TNF-α acts as a shared pro-inflammatory mediator implicated in both psoriasis and AD." (PMID 41465136, 2025). "In recent years, the management of moderate-to-severe psoriasis has been revolutionized by the introduction of biologic therapies targeting specific cytokines implicated in disease pathogenesis, including tumor necrosis factor alpha (TNF-α), interleukin-12/23 (IL-12/23), IL-17, and IL-23." (PMID 41010661, 2025). "In psoriasis, various stress-related triggers—ranging from environmental factors to genetic predispositions—can activate innate immune cells and keratinocytes to produce tumor necrosis factor-α (TNF-α), interferon-γ (IFN-γ), IFN-α, interleukin-6 (IL-6), and interleukin-1β (IL-1β)." (PMID 40731810, 2025). "Moreover, systemic inflammation in patients with psoriasis, including elevated serum proinflammatory cytokines (e.g.,TNF-α, IL-17, and IL-23) may contribute to an increased risk of atherosclerosis, hypertension, alteration of serum lipid composition, and IR." (PMID 40977704, 2025). "Furthermore, studies suggest that the Th1 cytokine TNF-a may also be implicated in this process, as treatment with anti-TNF-a agents has led to improvement in both itch and mood symptoms, including stress, especially in psoriasis." (PMID 39597998, 2024). "Considering phototherapy on one hand, which exerts a direct damaging effect on keratinocytes, and immunosuppression induced by anti-TNFα agents on the other, patients with psoriasis may be exposed to two of the best-known risk factors for developing NMSCs during their lifetime." (PMID 38730981, 2024).
psoriasis (continued). "Furthermore, a recent Mendelian randomization study has provided evidence suggesting that a genetic predisposition to inflammatory pathways, such as those involving TNF-α and IL-17, may underlie the observed comorbidity between periodontitis and psoriasis." (PMID 39189252, 2024). "Based on this, the pathogenesis of psoriasis involving the IFNα-TNFα-IL-23-IL-17 pathway suggests that the elevated levels of IFNα in severe psoriasis cases might be further increased by TNF inhibitors, potentially heightening the risk of autoantibody production." (PMID 38987260, 2024). "However, IL-1ra has also been shown to upregulate before the onset of many inflammatory diseases, such as type 2 diabetes mellitus and psoriasis, which may be related to the early compensatory response to inflammation caused by IL-1 and TNF." (PMID 38327497, 2024). "The pathway causing inflammation from psoriasis begins with genetic predisposition and/or a triggering environment factor that damages keratinocyte leading to release of interleukin 1, interleukin 6 and tumor necrosis factor α and also leading to the activation of dendritic cells." (PMID 39274352, 2024). "Additionally, we quantified the reported odds ratios and their 95% confidence intervals between four individual TNF inhibitors and found that the degree of association with psoriasis was variable among the drugs studied, with certolizumab pegol exhibiting the highest reported risk." (PMID 37369753, 2023). "Patients with psoriasis, have shown a significantly increased risk of AD when compared with healthy controls whilst therapeutics for psoriasis are being investigated for their possible impact on AD, with TNF blocking agents associated with lower risk of AD for." (PMID 37382595, 2023). "Furthermore, a study of patients with juvenile idiopathic arthritis, IBD, or psoriasis that used a Medicaid database hinted at a similar, albeit non-significant, increase in the risk of lymphoma in patients receiving TNFα inhibitor treatment (adjusted HR 2.64, 95% CI 0.93–7.51)." (PMID 37554981, 2023). "In addition, a high incidence of anti-TNF-associated psoriasis in patients treated with IFX or ADA was confirmed in further analyses, which also documented an association with female gender, foregut disease location, fistulising, and stricturing disease behaviour." (PMID 37175894, 2023). "BS-EAcf can inhibit immune pathways associated with TNF-α-induced acute and chronic inflammatory responses by psoriatic keratinocytes, suggesting that the molecules contained in the aqueous extract from Picea mariana bark had a therapeutic potential to treat psoriasis." (PMID 36903291, 2023). "Thus, TNF-α/IL-17A/IFN-γ induced a psoriasis condition, ultimately causing skin hyperkeratosis." (PMID 36015080, 2022). "However, the association between the use of anti-TNF agents and the development of psoriasis in patients with IBD remains unclear." (PMID 35801760, 2022). "However, long-term TNF-α blockage could also induce side effects, especially increasing the risk of pediatric patient with psoriasis." (PMID 36618400, 2022). "Therefore, we believe that this study might be the first to comprehensively examine the association between anti-TNF therapy and paradoxical psoriasis development in patients with IBD." (PMID 35801760, 2022). "This article reviews the recent literature on PRs associated with TNF-α, interleukin (IL)-12/23 (p40), IL-17A/the IL-17 receptor (R), IL-23 (p19), and IL-4Rα inhibitors, which are commonly used for dermatological conditions, especially atopic dermatitis (AD) and psoriasis." (PMID 35884790, 2022). "Finally, it is worth highlighting the only study that has evaluated the influence of the presence of particular genetic polymorphisms on susceptibility to developing toxicity and/or paradoxical psoriasis due to anti-TNF drugs, conducted in 161 Spanish patients diagnosed with plaque psoriasis." (PMID 33921427, 2021).
psoriasis (continued). "Neutralization of TNF and/or IL-17 with mAbs revealed that both can recover growth and pigment production of melanocytes, which may contribute to pigmentation changes associated with psoriasis treatment." (PMID 33921371, 2021). "In addition, our analysis identified a strong association between HS and psoriasis, which may be driven in part by the shared upregulation of TNF-α, IL-12/23, and IL-17 in both diseases." (PMID 34546979, 2021). "Finally, in the interleukin 23 receptor (IL23R) gene, the IL23R rs11209026 polymorphism has shown an influence on the response to anti-TNF drugs in naive patients and on the risk of developing toxicity and/or paradoxical psoriasis through the anti-TNF treatment." (PMID 34577605, 2021). "Whereas Reg-1 was recently reported to negatively regulate IL-23/IL-17 transcript levels at early stages of IMQ-driven experimental psoriasis our data suggest that Reg-3 might also reduce pathogenic inflammation by directly controlling TNF turnover in psoriasis." (PMID 34298932, 2021). "Additionally, our present findings may also account for the previous observation that the Asian AD phenotypes have features of psoriasis with increased Th17 polarization, which were linked to TNF-α exposure." (PMID 33497363, 2021). "However, since in addition to the treatment of RA, monoclonal antibodies have been shown to be effective in treating Crohn’s disease, psoriasis, and other diseases associated with TNF-α overexpression, it is possible to compare the results of ASO testing against TNF-α in a model of chronic colitis." (PMID 33498456, 2021). "Moreover, decreased expression of filaggrin in the lesional skin of psoriasis due to secreted cytokines including IL-4, IL-13, IL-17, and TNF-α might increase the risk of skin cancer by increasing UV sensitivity of patients with psoriasis." (PMID 32987907, 2020). "However, the exact mechanisms involved in the effects of pathogenic cytokines in psoriasis and antipsoriatic treatment with TNF-α antagonists remain unclear." (PMID 32280718, 2020). "In the DEX group, the expressions of IL-1β, IL-6, TNF-α, IL-17, and IL-22 were significantly lower than the model group (p < 0.05), suggesting that the expressions of inflammatory cytokines associated with psoriasis have been inhibited after the intervention of DEX." (PMID 32090080, 2020). "Despite roles in defense mechanism against inflammatory conditions, TNF-α is well characterized as a pathogenic mediator in diverse inflammatory diseases, including Alzheimer’s disease (AD), Parkinson’s disease (PD), stroke, psoriasis, arthritis, septic shock, and pulmonary disorders." (PMID 31991572, 2020). "Increased levels of TNF-α and IL-6 before the onset of infection are associated with an increased risk of pneumonia requiring hospitalization, suggesting that overproduction of these cytokines can trigger bacterial invasion and the development of pneumonia in patients with psoriasis." (PMID 32987907, 2020). "Direct IL-17 inhibition with monoclonal antibodies in patients with psoriasis or psoriatic arthritis has been shown to increase the risk of candida infections; similarly, the reactivation of latent tuberculosis infection was observed in patients treated with TNF-inhibitors." (PMID 31295952, 2019). "Additionally, a positive association between TNF-α and BMI in psoriasis was demonstrated." (PMID 31521168, 2019). "Interestingly, Wittmann’s group has recently demonstrated that IL-36R activation by IL-36γ induces the production of psoriasis-associated cytokines (i.e., IL-23 and TNF-α) from human macrophages, and that this response is enhanced in macrophages from psoriasis patients." (PMID 31284527, 2019). "The future identification of specific genetic variants potentially involving pDC activation and/or type I IFN signaling may provide an explanation for an increased susceptibility of these individuals to develop paradoxical psoriasis in the context of anti-TNF treatment." (PMID 29295985, 2018).